RNU6-330P (RNA, U6 small nuclear 330, pseudogene)
Gene: Small nuclear RNA gene on chromosome X (74,680,053 to 74,680,159, forward strand). Ensembl gene ENSG00000199885.
Homologues: Orthologues: chimpanzee U6 (97% identical), macaque U6 (95% identical), mouse Gm25078 (79% identical), rabbit U6 (78% identical), rabbit U6 (72% identical). Paralogues in human: RNU6-836P (88% identical), RNU6-1124P (87% identical), RNU6-41P (87% identical), RNU6-1029P (86% identical), RNU6-1122P (86% identical), RNU6-116P (86% identical), RNU6-1251P (86% identical), RNU6-29P (86% identical), RNU6-49P (86% identical), RNU6-1011P (85% identical), RNU6-10P (85% identical), RNU6-1169P (85% identical), and 1285 more.